OR6L1P (olfactory receptor family 6 subfamily L member 1 pseudogene)
Gene: Unprocessed pseudogene on chromosome 10 (133,575,122 to 133,576,031, reverse strand). Ensembl gene ENSG00000233685.
Diseases named in the same sentence as OR6L1P in open-access papers:
OR6L1P is named in the same sentence as 1 disease in open-access papers, as found by Europe PMC text mining. Sharing a sentence is not in itself a finding about the gene and the disease.
OR6L1P shares sentences with these, for which no sentence is quoted: autism (1 paper).